VEGFC (vascular endothelial growth factor C)
Diseases named in the same sentence as VEGFC in open-access papers (continued):
Sharing a sentence is not in itself a finding about the gene and the disease.
melanoma (80 papers, 2004 to 2026). A malignant, usually aggressive tumor composed of atypical, neoplastic melanocytes. "Together, these findings identify miR-374b-5p as a novel regulator of melanoma progression that acts through VEGFC-associated MAPK signaling and tumor microenvironment reprogramming, identifying miR-374b-5p as a promising therapeutic candidate for melanoma." (PMID 41898713, 2026). "In other skin cancers such as melanoma, it has also been seen that the protein expression of VEGFC is an important risk factor and predictor in this cancer." (PMID 38203550, 2023). "Several studies have confirmed that the net benefit of VEGFC release from melanoma cells and tumor-associated macrophages (TAM) to induce lymphangiogenesis is to promote LN metastasis of melanoma, which is considered a marker of a poor prognosis of melanoma." (PMID 36831512, 2023). "increase vascular endothelial growth factor C (VEGFC) secretion in association with cutaneous vasoproliferative tumor growth (bacillary angiomatosis, peliosis hepatis), which is also an important melanoma growth factor." (PMID 33802018, 2021). "In a mouse model, overexpression of VEGFC in the lung promoted lymphatic infiltration and lung metastasis of melanoma, with more metastasis to other distant organs." (PMID 36831512, 2023). "Esomeprazole has also been shown to inhibit melanoma growth by inactivating NF-κB to downregulate vascular endothelial growth factor-C (VEGF-C) expression." (PMID 36225582, 2022). "Bartonella henselae co-cultured with melanoma cells induced production of VEGFC and interleukin 8 (IL-8)." (PMID 33802018, 2021). "VEGFC was significantly upregulated at 24 h in B. henselae-infected melanoma cells as compared to melanoma cells alone." (PMID 33802018, 2021). "Using confocal microscopy techniques, the study has shown co-localization of B. henselae with vascular endothelial growth factor C (VEGFC), a melanoma growth factor, in the skin biopsy tissues from the patients with melanoma." (PMID 34201011, 2021). "The finding that VEGFC is upregulated in melanoma cells co-cultured with B. henselae is similar to previously reported studies of B. henselae co-cultures with endothelial or HeLa cells." (PMID 33802018, 2021). "Using a co-culture model, B. henselae was observed to enter melanoma cell cytoplasm and resulted in increased vascular endothelial growth factor C (VEGFC) and interleukin 8 (IL-8) production." (PMID 33802018, 2021). "Specifically, BACH1 and VEGFC expression are significantly higher in samples from melanoma patients clinically diagnosed with lymph node metastatic spread, as compared with those with primary tumors." (PMID 32132179, 2020). "In addition, VEGFC acts as a signaling ligand for integrin α9β1 that can stimulate the focal adhesion of melanoma cells." (PMID 36766725, 2023). "Melanoma cells have metastatic characteristics activated by signalling pathways that are activated by receptor phosphorylation induced by growth factors (vascular endothelial growth factor‐C (VEGF‐C) and transforming growth factor‐beta (TGF‐β1))." (PMID 36398426, 2022). "It has been reported that VEGFC knockdown results in reduced PDGFB levels in melanoma cell lines." (PMID 34277450, 2021). "Interestingly, we found that BACH1 expression positively and significantly correlates with the expression of VEGFC in human melanoma and LUAD cancer progression." (PMID 32132179, 2020). "Vascular endothelial growth factor‐C (VEGF‐C) binds to receptor vascular endothelial growth factor receptor‐3 (VEGFR‐3) expressed on lymphatic endothelial and melanoma cells." (PMID 36398426, 2022). "In contrast to their expression in lung adenocarcinoma, VEGFC and PFGFC are upregulated by silencing MITF in melanoma cells, which is in accordance with MITF low-expression promoting metastasis because angiogenesis usually accelerates metastasis." (PMID 33293474, 2020).
melanoma (continued). "Enhanced reduced representation bisulfite sequencing‐based methylome profiling revealed for the first time a link between abnormal VEGFC, ANGPT2, and SIX1 gene expression and promoter hypomethylation in melanoma cells." (PMID 31069961, 2019). "The methylation status of VEGFC, ANGPT2, and SIX homeobox 1 (SIX1) promoters was also found to correlate with overall survival in melanoma patients." (PMID 31069961, 2019). "Furthermore, in melanoma, I-BET151 also inhibits the production of cytokines and chemokines, such as IL-1α, VEGFC, IL-6, and IL-8." (PMID 34540687, 2021). "Interestingly, in the presence of IFNγ and TNFα melanoma cells can also upregulate TGFB, IL10, VEGFA, and VEGFC genes, which can further modulate the immunosuppressive phenotype of TAMs." (PMID 32793228, 2020). "However, the genes ANXA1, PDGFC, VEGFC and LRRN3 were downregulated in CL1-0 shMITF-harboring cells, while they were upregulated in si-MITF melanoma 501MEL cells." (PMID 33293474, 2020). "Moreover, we identified VEGFR‐3 and ANGPT2 expression, as well as VEGFC, ANGPT2, and SIX1 promoter methylation, as independent prognostic factors for overall survival in melanoma patients, showing the high translational relevance of our findings obtained in a murine model." (PMID 31069961, 2019). "Vascular endothelial growth factor C and -D staining were apparent in these samples, but there were no qualitative differences in the intensity of staining for VEGF-C or VEGF-D in metastatic vs nonmetastatic melanoma samples, as has been reported in other small-scale studies." (PMID 14760386, 2004).
lung carcinoma (72 papers, 2001 to 2025). "Another amplified lncRNA, PVT1 (plasmacytoma variant translocation, regulates VEGFC (vascular endothelial growth factor C) by acting as a ceRNA for miR‐128 in lung cancer with elevated expression being associated with poor survival." (PMID 40783798, 2025). "VEGFC, an activator of lymphatic vessel formation, has been considered as a risk factor for lung cancer and has been associated with a poor prognosis in lung cancer patients." (PMID 37187731, 2023). "Initially, using the lung cancer dataset, it was identified in VEGFC and proteins from the treatment datasets: RXRA, PPARG, and SMO." (PMID 40334012, 2025). "The over-expression of CCL4 in oral squamous cell carcinoma and lung cancer increased lymphangiogenesis and vascular endothelial growth factor c expression and PD-L1." (PMID 38067251, 2023). "Tumor necrosis family superfamily member 15 (TNFSF15) promotes lymphatic metastasis by upregulating vascular endothelial growth factor-C in a lung cancer mouse model." (PMID 38022627, 2023). "For instance, while the VEGFC/Flt4 pathway unregulated CNTN1 expression in lung cancer, CNTN1 upregulation in prostate cancer is an outcome of the conversion of non-CSC PC cells to PCSC and CNTN1 in turn contributes to PCSC-derived metastasis." (PMID 32752094, 2020). "Taken together, these data indicated that EGFR-TKIs mediate lung cancer cell VEGFC expression, which further regulates lymphatic vessel formation." (PMID 31892990, 2020). "As a mechanism of lymph node metastasis, IL-17 can promote lymphangiogenesis by upregulating the expression of the lymphangiogenic factor vascular endothelial growth factor-C (VEGF-C) in murine lung cancer cells." (PMID 27784305, 2016). "Cyclooxygenase-2 (COX-2) has recently been considered to promote lymphangiogenesis by up-regulating vascular endothelial growth factor-C (VEGF-C) in breast and lung cancer." (PMID 21272377, 2011). "As these pathways exhibit compensatory activation upon cabozantinib treatment in resistant cells, we investigated whether VEGFC/KDR/NRP2 knockdown elicited a decrease in FGF/YAP/TAZ/AXL expression in resistant lung cancer cells." (PMID 40843133, 2025). "Indeed, we found that the expression of VEGFC in lung cancer tissues was significantly higher than that in healthy lung tissues." (PMID 35371324, 2022). "Thus, to assess whether the mechanism of exercise inhibiting tumor growth and metastasis is associated with tumor angiogenesis and lymphangiogenesis, we detected the protein expression of CD105, Vascular endothelial growth factor-A (VEGFA), and VEGFC lung cancer tissues." (PMID 35371324, 2022). "This revealed that the VEGF-C gene was amplified in 22% (13/59; range between 3–5 copies of VEGFC), present as 2 copies in 54% (32/59), and deleted in 24% (14/59) of the lung cancer cell lines that we analyzed." (PMID 26950548, 2016). "Further, patients with lung cancer with a positive VEGFC expression were significantly more likely to develop brain metastases than those with a negative VEGFC expression." (PMID 35903112, 2022). "We explored the expression of the VEGFA, VEGFC, and VEGFD proteins in lung cancer and adjacent tissues and showed that VEGFA, VEGFC, and VEGFD were substantially highly expressed in lung cancer tissues, which may be the main source of VEGF-related protein expression in TDLNs." (PMID 40693467, 2025). "Unfortunately, we found that neither MICE nor HIIE reduced the expression of VEGFA and VEGFC in lung cancer tissues, indicating that neither MICE nor HIIE control proliferation and metastasis of tumor cells by angiogenesis and lymphangiogenesis in tumor tissues." (PMID 35371324, 2022). "After 24 h, the three inhibitors significantly inhibited the secretion of VEGFC by HCC827 cells; after 9 hours, we also observed an inhibitory effect, which in turn hindered the formation of lymphatic vessels in the tumours and slowed the lymphatic metastasis of lung cancer cells." (PMID 31892990, 2020).
lung carcinoma (continued). "However, neither the MICE group nor the HIIE group could reduce the expression level of VEGFC, which means that MICE and HIIE cannot inhibit lymphangiogenesis in lung cancer tissues." (PMID 35371324, 2022).
colorectal cancer (68 papers, 2000 to 2025). A primary or metastatic malignant neoplasm that affects the colon or rectum. "In human colorectal cancer, expression of VEGFC/VEGFR3 is increased, whereas levels of VE-cadherin are lower than in normal tissues." (PMID 38148112, 2024). "Overall, VEGFC plays a multifaceted role in colorectal cancer, influencing both tumor growth and metastasis, and it represents a promising target for therapeutic interventions aimed at controlling disease progression." (PMID 39328205, 2024). "Among the prognostic risk factors, SNRPA1 was reported to be highly expressed in colorectal cancer tissues and promoted cancer progression through the regulation of PIK3R1, VEGFC, MKI67, and CDK1." (PMID 36212157, 2022). "A good deal of circRNA/miRNA/mRNA regulatory networks have been unraveled in human cancers, like circAPLP2/miR-485-5p/FOXK1 in colorectal cancer and circMYLK/miR-513a-5p/VEGFC in renal cell carcinoma." (PMID 34287578, 2021). "Previous studies have shown that BACH1 promotes angiogenesis by modulating VEGFC expression in ovarian cancer and colorectal cancer." (PMID 33932125, 2021). "Some studies have shown that miR-27b inhibits tumor progression and angiogenesis in colorectal cancer by targeting VEGFC." (PMID 33015156, 2020). "These genes, including HIF1-α, VEGF receptors Flt1 and KDR, and VEGFC, suggest an association of FJX1 and angiogenic gene expression in human colorectal cancer tumor samples." (PMID 23922772, 2013). "In the present study, we investigated the potential pro-lymphangiogenesis effects of extra domain A (EDA)-mediated vascular endothelial growth factor-C (VEGF-C) secretion in colorectal carcinoma (CRC)." (PMID 22496919, 2012). "The induction of various inflammatory factors such as vascular endothelial growth factor C (VEGFC) could mediate endothelial cell activation during colorectal cancer invasion." (PMID 34222020, 2021). "Thus, the reduction of VEGFC expression in the colorectal cancer cell line HT29 is the evidence of a potential antiangiogenic and antimetastatic effects of LCS-1269." (PMID 34885910, 2021). "VEGFC can disrupt the endothelial lymphatic barrier to promote colorectal cancer invasion." (PMID 31892990, 2020). "The SAM programme typed mRNA of transcripts of the VEGFA, VEGFC, and CCND1 encoding genes to be statistically significant in the compared groups as genes differentiating stages III and IV of clinical progression of colorectal cancer." (PMID 22363883, 2011).
bladder cancer (54 papers, 2007 to 2026). "Five of the top nine significant SNPs were in VEGFC, which is known to have important functions contributing to bladder cancer risk." (PMID 23251617, 2012). "Association between VEGFC haplotypes and bladder cancer risk." (PMID 23251617, 2012). "For instance, IL-6 and IL-17 regulate VEGFC expression via the PI3K-Akt or extracellular-signal-regulated kinase (ERK) 1/2 pathways, whereas MicroRNA-1826 significantly down-regulates VEGFC expression in human bladder cancer." (PMID 32132179, 2020). "Moreover, enhanced expression of CCL2 induces TAM activation and M2 polarization, which ultimately contribute to lymphangiogenesis and lymph node metastasis of bladder cancer cells by secreting vascular endothelial growth factor C (VEGF-C)." (PMID 36263199, 2022). "Intriguingly, lncRNA BLACAT2 (bladder cancer-associated transcript 2) is also able to bind directly to WDR5, but it promotes lymphangiogenesis and lymphatic metastasis of bladder cancer by enhancing the expression of VEGF-C (vascular endothelial growth factor C)." (PMID 33520725, 2020). "miR-122 serves as a tumor suppressor and downregulator of vascular endothelial growth factor C (VEGFC) expression, leading to the inhibition of bladder cancer growth and angiogenesis." (PMID 37686525, 2023). "This study was conducted to determine miR-101’s role on the lymphangiogenic molecule vascular endothelial growth factor C (VEGF-C) and their effects upon bladder cancer cell migration, invasion, and chemosensitivity to cisplatin." (PMID 25658842, 2015). "Their findings demonstrate how miR-122 controlled cell proliferation via the VEGFC/AKT/mTOR signaling cascade, and they suggest that exogenous miR-122 overexpression may be a feasible method for targeted bladder cancer treatments." (PMID 36803831, 2023). "Also, BCYRN1 increases VEGFC and its receptor (VEGF‐C/VEGFR3) signaling in bladder cancer patients with lymph node metastatic." (PMID 36463254, 2022). "Moreover, the effects induced by KD of candidates including SHC1, VEGFC, VEGFR3, and ERK1/2 were evaluated by cell proliferation assay, displaying SHC1 as the strongest inhibitor of bladder cancer proliferation." (PMID 33203836, 2020). "The lncRNA BLACAT2 is markedly upregulated in metastatic bladder cancer cells, and BLACAT2 upregulates vascular endothelial growth factor C (VEGF-C) expression by binding to WDR5, resulting in bladder cancer-associated lymphangiogenesis and lymphatic metastasis." (PMID 30488017, 2018).
cervical carcinoma (49 papers, 2001 to 2025). A carcinoma arising from either the exocervical squamous epithelium or the endocervical glandular epithelium. "In our study, we observed that the expression of VEGFC was significantly increased in the CM collected from the TNF-α-treated cervical cancer cells." (PMID 37124061, 2023). "The aim of the present study was to investigate the effect of heat shock protein 90 (Hsp90)-specific inhibitor geldanamycin (GA) on the proliferation and apoptosis induced by vascular endothelial growth factor-C (VEGF-C) in cervical cancer cells." (PMID 25289059, 2014). "The elevated expression of vascular endothelial growth factor C (VEGF-C) is correlated with clinical cervical cancer metastasis and patient survival, which is interpreted by VEGF-C functions to stimulate angiogenesis and lymphatic genesis." (PMID 20429915, 2010). "In general, TNF-α could promote cervical cancer tumorigenesis, lymphangiogenesis, and lymphatic metastasis in vivo via activating VEGFC-mediated AKT and ERK pathways." (PMID 37124061, 2023). "Our findings suggest that TNF-α could be apromising target for cervical cancer treatment, as it promote lymphangiogenesis and lymphatic metastasis by upregulating VEGFC." (PMID 37124061, 2023). "In this study, we only determined that TNF-α could inhibit cervical cancer progression by targeting VEGFC-mediated AKT and ERK pathways." (PMID 37124061, 2023). "Collectively, TNF-α could promote tumorigenesis, lymphangiogenesis, and lymphatic metastasis in vitro and in vivo in cervical cancer via activating VEGFC-mediated AKT and ERK pathways." (PMID 37124061, 2023). "We found that TNF-α significantly stimulated cervical cancer cells to secrete VEGFC." (PMID 37124061, 2023). "The role of galectin-3 in vascular endothelial growth factor C (VEGF-C)-induced cervical cancer cell invasion has been previously investigated, and silencing of galectin-3 expression with specific siRNA largely impaired VEGF-C-enhanced invasion in cervical carcinoma cell line." (PMID 28355349, 2017). "Furthermore, this study showed that TNF-α could stimulate cervical cancer cells to secrete VEGFC, which in turn promoted the proliferation, migration, and angiogenesis of HLECs." (PMID 37124061, 2023). "An in vitro experiment showed that RhoA is involved in tumor migration via the VEC (Vascular endothelial growth factor C, VEGF-C)–RhoA–ROCK2 signaling pathway and correlates with cervical cancer metastasis." (PMID 31976530, 2020). "Furthermore, TNF-αelevated D2-40 and VEGFC protein expressions in tumor tissues, indicating that TNF-α could promote lymphangiogenesis and lymphatic metastasis of cervical cancer in vivo." (PMID 37124061, 2023).